TSHB (thyroid stimulating hormone subunit beta)
Description:
Indispensable for the control of thyroid structure and metabolism.
Synonyms: TSH-B; TSH-beta
Tractability: Small molecule: a structure with a bound ligand is known. Antibody: its Gene Ontology location is reachable by antibodies, with high confidence; UniProt places it where antibodies can reach, with medium confidence; UniProt predicts a signal peptide or a membrane-spanning region.
Gene: Protein-coding gene on chromosome 1 (115,029,826 to 115,034,302, forward strand). Ensembl gene ENSG00000134200.
Subcellular location: Secreted
Pathways (Reactome):
Signal Transduction: G alpha (s) signalling events; Hormone ligand-binding receptors
Metabolism: Thyroxine biosynthesis
Metabolism of proteins: Glycoprotein hormones
Gene Ontology:
Molecular function: hormone activity
Biological process: anatomical structure morphogenesis; cell-cell signaling; G protein-coupled receptor signaling pathway; cell communication; signaling
Cellular component: extracellular region
Genetic constraint (gnomAD): Loss-of-function variants: 9 observed, 10.15 expected, observed/expected ratio (o/e) 0.89, 90% interval 0.53 to 1.53. The upper end of that interval is the gene's LOEUF score, 1.53, which puts it in group 6 of 6, group 1 being the genes least tolerant of losing a copy. Missense variants: 182 observed, 178.55 expected, observed/expected ratio (o/e) 1.02, 90% interval 0.9 to 1.15. Synonymous variants: 57 observed, 60.6 expected, observed/expected ratio (o/e) 0.94, 90% interval 0.76 to 1.17.
Homologues: Orthologues: chimpanzee TSHB (98% identical), macaque TSHB (98% identical), dog TSHB (91% identical), rabbit TSHB (91% identical), pig TSHB (88% identical), mouse Tshb (85% identical), rat Tshb (85% identical), guinea pig TSHB (80% identical), tropical clawed frog tshb (60% identical), zebrafish tshba (41% identical), Drosophila melanogaster Gpb5 (19% identical). Paralogues in human: LHB (37% identical), CGB3 (36% identical), CGB5 (36% identical), CGB7 (36% identical), CGB8 (36% identical), CGB1 (36% identical), CGB2 (36% identical), FSHB (36% identical), GPHB5 (24% identical).
Diseases named in the same sentence as TSHB in open-access papers:
TSHB is named in the same sentence as 23 diseases in open-access papers, as found by Europe PMC text mining. Sharing a sentence is not in itself a finding about the gene and the disease. The quoted sentences say what the papers report.
hypothyroidism (9 papers, 2011 to 2025). Abnormally low levels of thyroid hormone. "A meta-analysis of all recorded pre-treatment FT4 values underlines the severity of hypothyroidism due to biallelic TSHB variants." (PMID 34566885, 2021). "TSHB is the key factor for the clinical diagnosis for hypothyroidism, while TG is the response protein to TSHB that drives the normal physiological behaviors of releasing thyroid hormones." (PMID 39897058, 2025). "For hypothyroidism, the first two features in the disease-specific ITCs were the TSHB (thyroid stimulating hormone beta) and TG (thyroglobulin), both of which were not included in the disease's genes." (PMID 39897058, 2025). "NCoR1 was enriched to the R1 in hypothyroidism when TSHβ gene transcription was increased and enriched to R2 in hyperthyroidism for repression of TSHβ gene transcription." (PMID 34237030, 2021). "The THRB K146Q mutation altered the recruitment of transcription factors to the TSHβ gene promoter, compared with WT, in hyperthyroidism and hypothyroidism." (PMID 34237030, 2021). "Because TSHβ expression in the pituitary thyrotroph increases in hypothyroidism, one would presume that unliganded TR activates the TSHβ gene." (PMID 24781449, 2014). "Although thyroidectomy caused severe hypothyroidism in TRH-deficient mice, the increases in serum TSH levels and pituitary TSHβ mRNA levels were insufficient." (PMID 22792320, 2012). "To evaluate the mechanism of the insufficient increase in the serum TSH levels in TRHKO in response to hypothyroidism induced by thyroidectomy, we measured TSHβ and α mRNA levels in the TRHKO pituitary and compared them to those in the wild-type." (PMID 22792320, 2012). "First, TRβ-knockout mice and wild-type mice exhibited comparable TSHβ expression in hypothyroidism where TRH secretion from the hypothalamus is elevated." (PMID 21533184, 2011). "T3 inhibits transcription of the TSHβ gene via thyroid hormone receptor (TR), and TSHβ expression increases in patients with hypothyroidism." (PMID 21533184, 2011). "This is supported by the report that pituitary-specific GATA2-knockout mice exhibit reduced TSHβ expression in hypothyroidism, where stimulation by TRH should be elevated." (PMID 21533184, 2011). "It is necessary to mention one of such example, which was TSHB for hypothyroidism." (PMID 39897058, 2025). "Furthermore, a recent study of pituitary-specific GATA2 Knockout mice demonstrated reduced pituitary TSH content and serum TSH levels, and pituitary TSHβ mRNA showed a defective response to hypothyroidism." (PMID 22792320, 2012). "Correspondingly, we observe colocalization of a known trans pQTL for TSHB (rs7695810; MAF = 0.181; beta = − 0.105; SE = 0.012; P = 3.89 × 10–18) with signals for self-reported hypothyroidism (PP4 = 92.6%) and treatment for hypothyroidism (91%)." (PMID 37550624, 2023). "Second, TSH level in hypothyroidism was severely impaired in TRH/TRβ-double knockout mice compared with wild-type or TRβ-knockout mice, suggesting that elevation of TSHβ expression requires the TRH signal even when inhibition by T3/TR is released." (PMID 21533184, 2011). "Although a biallelic defective TSHB leads to severe hypothyroidism, this is not the case in defective TRHR." (PMID 34566885, 2021). "Interestingly, a study conducted on male rats with hypothyroidism showed that kisspeptin, another hormone belonging to the RF-amide family, did not affect TSHβ mRNA expression in pituitary cells." (PMID 39774489, 2025).
Central hypothyroidism (8 papers, 2011 to 2025). A type of hypothyroidism due to an insufficient stimulation of an otherwise normal thyroid gland. "We report three kindreds from the UK or Ireland in which four cases exhibit isolated central hypothyroidism secondary to TSHB mutations." (PMID 27362444, 2017). "Despite having been discovered only recently, this syndrome already encompasses more unique mutations and patients than all other known genetic causes of isolated central hypothyroidism combined (TSHB [12, –, 16] and TRHR)." (PMID 26840047, 2016). "As well as expanding the known repertoire of TSHB mutations, our observations suggest that TSHB deletions may be more common than previously thought and show that c.373delT TSHB mutation is the most common genetic defect in cases of central hypothyroidism in the UK and Ireland." (PMID 27362444, 2017). "Isolated congenital central hypothyroidism (CeH) can result from mutations in TRHR, TSHB, and IGSF1, but its etiology often remains unexplained." (PMID 27603907, 2016). "Isolated central hypothyroidism is a rare entity, with an estimated incidence of 1:65 000 and known genetic causes affect the TSH biosynthetic pathway, comprising mutations in TSHB and TRHR, and IGSF1." (PMID 26416826, 2015). "We report on a girl with isolated central hypothyroidism due to a homozygous one-base pair deletion (T313del) in exon 3 of the TSHβ subunit gene." (PMID 22606512, 2011). "Direct sequencing of the coding exons and exon/intron boundaries of three candidate genes for central hypothyroidism (TSHB, CGA and TRHR) revealed no genetic abnormalities." (PMID 28262687, 2017).
congenital hypothyroidism (6 papers, 2018 to 2025). A thyroid hormone deficiency present from birth. "Isolated CCH is a rare variant of congenital hypothyroidism, the majority of cases isassociated with mutations in the TSHB gene (OMIM#188540), and the inheritance isautosomal recessive." (PMID 31166470, 2019). "Of note, patients with the naturally occurring mutation c.313delT (C105Vfs114X) in the TSHB-gene show extraordinary early and severe signs of congenital hypothyroidism." (PMID 31703413, 2019). "Patients with the mutation C105Vfs114X in the TSHB-gene show severe clinical signs of congenital hypothyroidism in the neonatal period and early infancy and psychomotor as well as neurological retardation if not detected and substituted with L-thyroxine early in life." (PMID 31703413, 2019). "Bi-allelic loss-of-function mutations in TSHB, encoding the beta subunit of thyroid-stimulating hormone (TSH), cause congenital hypothyroidism." (PMID 34981755, 2022). "Loss-of-function mutations in TSHB, encoding the TSHβ subunit, result in biologically inactive TSH and congenital hypothyroidism (OMIM 275100)." (PMID 28853052, 2018).
central congenital hypothyroidism (5 papers, 2017 to 2026). Central or secondary congenital hypothyroidism is a type of permanent congenital hypothyroidism characterized by permanent thyroid hormone deficiency that is present from birth and secondary to a disorder in the thyroid-stimulating hormone (TSH) - thyrotropin-releasing hormone (TRH) system. "The TSHB mutation C105Vfs114X leads to isolated thyroid-stimulating-hormone-(TSH)-deficiency and results in a severe phenotype." (PMID 31703413, 2019). "One of the molecular causes for CCH are mutations in the TSHB-gene, which cause isolated TSH deficiency." (PMID 31703413, 2019). "Four cases of isolated TSH deficiency from three unrelated families in the UK and Ireland were investigated for mutations or deletions in TSHB." (PMID 27362444, 2017). "Homozygous mutations in the TSH beta subunit gene (TSHB) result in severe, isolated, central congenital hypothyroidism (CCH)." (PMID 27362444, 2017). "This study, including the identification of a second, novel, TSHB deletion, expands the molecular spectrum of TSHB defects and suggests that allele loss may be a commoner basis for TSH deficiency than previously suspected." (PMID 27362444, 2017).
hyperthyroidism (3 papers, 2021 to 2023). Overactivity of the thyroid gland resulting in overproduction of thyroid hormone and increased metabolic rate. "Since the opposite condition, hyperthyroidism, is a known cause of atrial fibrillation, it is consistent that increased levels of TSHB would be inversely associated with the arrythmia." (PMID 37550624, 2023). "Medical record review of a cohort of individuals homozygous for the R75G TSHB variant revealed that because of the falsely undetectable TSH levels many of them have been incorrectly diagnosed with hyperthyroidism and treated, similar to our index case." (PMID 34981755, 2022). "This could possibly reflect the interindividual variability of the normal TSH levels, and suggest that the presence of the R75G TSHB variant could be erroneously interpreted as subclinical hyperthyroidism in heterozygous carriers as well." (PMID 34981755, 2022). "Clinically, individuals homozygous for the R75G TSHB variant cannot be distinguished from patients with subclinical hyperthyroidism, defined biochemically as having normal serum free thyroxine (T4) and triiodothyronine (T3) concentrations in the presence of a subnormal serum level of TSH." (PMID 34981755, 2022).
autoimmune thyroid disease (2 papers, 2021). Inflammatory disease of the thyroid gland due to autoimmune responses leading to lymphocytic infiltration of the gland. "For example, the alternatively spliced variant of thyroid stimulating hormoneβ (TSHβ), TSHβv (exon 2 deleted, exon 3 retained) has been associated with autoimmune thyroiditis in humans, which is also a high-risk factor for thyroid carcinoma." (PMID 34722250, 2021). "Also presented are the ways whereby the TSHβ splice variant may be a contributing factor in the development and/or perpetuation of autoimmune thyroid disease (AIT), and how systemic infection may elicit immune-endocrine responses." (PMID 33828532, 2021).
hypopituitarism (2 papers, 2023 to 2025). A condition of diminution or cessation of secretion of one or more hormones from the anterior pituitary gland. "There are many causative genes for its isolated form or for multihormonal hypopituitarism, such as TSHβ, TRHR, TBL1X and IRS4 (for heritable isolated central hypothyroidism) and PROP1, HESX1, SOX3 (for multihormonal hypopituitarism)." (PMID 39997750, 2025). "POU1F1 also induces differentiation of GH-, PRL-, and TSHB-producing cell lineages in the anterior pituitary and, when mutated, causes multiple pituitary hormone deficiency syndrome and hypopituitarism." (PMID 37600690, 2023).
athyreosis (1 paper, 2021). Athyreosis is a form of thyroid dysgenesis characterized by complete absence of thyroid tissue that results in primary congenital hypothyroidism, a permanent thyroid deficiency that is present from birth. "Patients with such a TSHb gene mutation show a severe phenotype compared to those with athyreosis." (PMID 34440752, 2021).
atrial fibrillation (1 paper, 2023). A disorder characterized by an electrocardiographic finding of a supraventricular arrhythmia characterized by the replacement of consistent P waves by rapid oscillations or fibrillatory waves that vary in size, shape and timing and are accompanied by an irregular ventricular response. "We highlight a protective role of increased levels of thyroid stimulating hormone subunit beta (TSHB) against atrial fibrillation." (PMID 37550624, 2023).
Encephalopathy (1 paper, 2026). Encephalopathy is a term that means brain disease, damage, or malfunction. "Whole-exome sequencing identified a homozygous pathogenic ADAR frameshift variant (NM_001111.5:c.2433_2434del) and a homozygous likely pathogenic TSHB variant (NM_000549.5:c.313T >C; p.Cys105Arg), confirming combined ADAR-related encephalopathy and isolated C-CH." (PMID 42256321, 2026).
Hashimoto thyroiditis (1 paper, 2016). An autoimmune disorder caused by the production of autoantibodies against thyroid tissue. "The identification of a TSHβ splice variant adds a level of complexity and intrigue to those activities, in particular because of the findings that TSHβv is the exclusive form of TSHβ made by the immune system, and because of its potential link to thyroid disease such as Hashimoto’s thyroiditis." (PMID 26771831, 2016).
osteoporosis (1 paper, 2021). A condition of reduced bone mass, with decreased cortical thickness and a decrease in the number and size of the trabeculae of cancellous bone (but normal chemical composition), resulting in increased fracture incidence. "For example, the extent to which native TSH and TSHβv work synergistically or antagonistically in delivering TSHR-mediated signals may provide important information into the specific role of TSHβ in AIT and osteoporosis." (PMID 33828532, 2021).
thyroid (1 paper, 2020). "First, the time course of the elevation of the rat prepro-TRH mRNA after the administration of an anti-thyroid drug, precisely correlates with that of TSHβ mRNA." (PMID 33201916, 2020).
thyroid agenesis (1 paper, 2025). "When thyroid agenesis is detected via thyroid scintigraphy, the presence of TSH receptor inactivating mutations, thyroid stimulating hormone subunit beta (TSHB) gene mutations, iodine retention defects and maternal thyrotropin receptor blocking antibodies should be considered." (PMID 39857886, 2025).
thyrotoxicosis (1 paper, 2011). A hypermetabolic syndrome caused by the elevation of thyroid hormone levels in the serum. "This is compatible with the recent report comparing Pax8-null mice with Pax8/TRH-R1 double knockout mice and the previous study that administration of TRH failed to stimulate TSHβ synthesis in a subject with overt thyrotoxicosis." (PMID 21533184, 2011).
vitamin A deficiency (1 paper, 2017). Deficiency of vitamin A due to malnutrition, malabsorption, or dietary lack. "This is consistent with the possibility that vitamin A deficiency suppresses activation of pituitary retinoid receptor, thereby increasing TSHB mRNA transcription which leads to high TSH secretion." (PMID 28194237, 2017).
TSHB also shares sentences with these, for which no sentence is quoted: thyroid cancer (2 papers); arrythmia (1); endocrine disorder (1); goiter (1); hematological disorders (1); infection (1); Listeria monocytogenes Infection (1).